KIF4A (kinesin family member 4A)
Diseases named in the same sentence as KIF4A in open-access papers (continued):
Sharing a sentence is not in itself a finding about the gene and the disease.
lung carcinoma (continued). "By employing proteomic approaches, we identified kinesin family member 4A (KIF4A), which was overexpressed in lung cancer, as a potential PHF14 binding-protein." (PMID 28160558, 2017). "Therefore, the identification of KIF4A as a regulator of PAI-1 provides valuable insight into the molecular mechanisms underlying cancer progression and emphasizes the potential of both KIF4A and PAI-1 as novel therapeutic targets in lung cancer and glioma." (PMID 38067227, 2023). "Taken together, these findings suggest that KIF4A regulates CSCs and EMT, which are involved in cancer recurrence and metastasis, indicating its potential value as a novel therapeutic target and prognostic marker in lung cancer and glioma." (PMID 38067227, 2023). "Because KIF4A had only weak effects in these additional lung cancer cell lines, it was not further studied." (PMID 29435157, 2018). "The roles of KIF4A, KIF11 and KIF2C in lung cancer have been already reported, while the involvement of KIF20A in LUAD remains largely unknown." (PMID 30105795, 2018). "In addition to the co-overexpression in lung cancer cells, PHF14 and KIF4A form a functional complex in native cells." (PMID 28160558, 2017). "The novel PHF14/KIF4A complex might indicate a fundamental interdependent role for PHF14 and KIF4A in the carcinogenesis of lung cancer." (PMID 28160558, 2017).
hepatocellular carcinoma (25 papers, 2013 to 2025). A malignant tumor that arises from hepatocytes. "In hepatocellular carcinoma (HCC) patients, KIF4A overexpression was associated with poorer overall and disease-free survival." (PMID 30254986, 2018). "In hepatocellular carcinoma (HCC), KIF4A is significantly elevated, with high levels associated with adverse clinicopathological features and reduced survival." (PMID 41361459, 2025). "For example, FOXM1 can promote the progression of hepatocellular carcinoma by upregulating KIF4A expression." (PMID 38937742, 2024). "A recent study has shown that KIF4A silencing suppresses AKT activation in hepatocellular carcinoma." (PMID 37039264, 2023). "KIF4A enhanced cell proliferation via activating Akt signaling in hepatocellular carcinoma; meanwhile, KIF4A downregulation dramatically decreased the expression of p-AKT in colorectal cancer." (PMID 34775374, 2021). "As for other tumor types, KIF4A has been reported to enhance carcinoma development by promoting cell cycle progression in vitro and in vivo in colorectal cancer and hepatocellular carcinoma." (PMID 33398330, 2021). "KIF4A expression level also retracted from TCGA liver cancer cohorts for external validation, and KIF4A expression was shown significantly increased in hepatocellular carcinoma tissue compared with normal liver tissue (p < 0.001)." (PMID 28646197, 2017). "In summary, our work identified KIF4A as a potential predictive and prognostic marker for hepatocellular carcinoma." (PMID 28646197, 2017). "Furthermore, multiple studies have demonstrated that KIF4A is closely correlated with the occurrence and development of various malignancies, such as lung adenocarcinoma, hepatocellular carcinoma, colorectal cancer, prostate cancer." (PMID 34034774, 2021). "Interestingly, high KIF4A expression was observed in certain cancer types, such as lung cancer, oral cancer, breast cancer, and hepatocellular carcinoma." (PMID 34775374, 2021). "FOXM1 promotes hepatocellular carcinoma progression by regulating KIF4A expression." (PMID 33261584, 2020). "The transcriptional activator Forkhead box M1 (FOXM1) has been shown to increase KIF4A expression in hepatocellular carcinoma (HCC)." (PMID 35312737, 2022). "Another member of the KIF2C family, KIF4A, is regulated by the transcription factor FOXM1 and has been shown to promote hepatocellular carcinoma cell proliferation." (PMID 38250721, 2024). "Our results indicated that a panel of E2F target gene signature, comprising of HN1, KIF4A, CDCA3, CDCA8 and SSRP1, is a reliable tool for predicting the overall survival of Hepatocellular carcinoma patients, and provided significant reference of clinical risk for Hepatocellular carcinoma patients." (PMID 35591857, 2022).
colorectal cancer (19 papers, 2018 to 2025). A primary or metastatic malignant neoplasm that affects the colon or rectum. "KIF4A, another hub gene identified herein, is reportedly upregulated in colorectal cancer tissues and cell lines and was significantly associated with patient clinicopathological features including OS and DFS herein." (PMID 32265985, 2020). "Increased expression of KIF4A is also associated with lymph node metastasis in colorectal cancer." (PMID 31788359, 2019). "KIF4A was found to be remarkably upregulated in primary colorectal carcinoma and contributes to the proliferation of colorectal carcinoma through modulation of p21-mediated cell cycle progression." (PMID 36837615, 2023). "The previous study revealed that KIF4A promotes cell proliferation by inducing p21-mediated cell cycle progression in colorectal cancer." (PMID 36499051, 2022). "In patients with colorectal cancer, KIF4A was upregulated, and downregulation of KIF4A reduced cell proliferation in colorectal cancer cells." (PMID 30254986, 2018). "KIF4A facilitates cell proliferation via induction of p21-mediated cell cycle progression and promotes metastasis in colorectal cancer." (PMID 29706624, 2018). "KIF14, KIF18B, KIF23, KIF4A, KNTC1, NCAPG2, and MCM3 regulate chromosomal integrity, mitotic spindle formation, and DNA replication, processes that are frequently dysregulated in colorectal cancer." (PMID 40405535, 2025). "However, little is known about the role of KIF4A in colorectal carcinoma (CRC)." (PMID 29706624, 2018).
prostate carcinoma (16 papers, 2019 to 2025). A carcinoma that arises from epithelial cells of the prostate gland. "In prostatic cancer (PCa), KIF4A levels are significantly elevated, particularly in castration-resistant PCa (CRPC) and advanced stages." (PMID 41361459, 2025). "An E2F target gene signature, formed by MDX3, PLK1, EPHA10, and KIF4A, exhibited a stronger predictive power than existing signatures in prostate cancer." (PMID 37854038, 2023). "Recent studies show that PLK1 and KIF4A as biomarkers have a high prognosis value in patients with prostate cancer." (PMID 35495629, 2022). "The four gene signatures (MDX3, PLK1, EPHA10, and KIF4A) showed a strong correlation with prostate cancer prognosis in cases selected from TCGA database." (PMID 35495629, 2022). "KIF4A knockdown was similar across this panel of cell lines and also similar to KIF4A knockdown in prostate cancer cells." (PMID 34326322, 2021). "We demonstrated through transcriptome profiling and genome-wide chromatin accessibility analysis that knockdown of KIF4A reveals gene signatures that are established to have profound effect on prostate cancer phenotypes." (PMID 34326322, 2021). "Our data demonstrated KIF4A and WDR62 are AR-independent prostate cancer driver genes that are associated with poor prognosis in patients with advanced metastatic disease." (PMID 34326322, 2021). "In localized primary human prostate cancer samples from the TCGA cohort, we observed that KIF4A and AR gene expression are correlated." (PMID 34326322, 2021). "To test the model that KIF4A is a prostate-specific driver gene, we generated a panel of diverse CRISPRi non-prostate cancer cell-line models (breast: MDA-MB-231i, ovarian: OVCAR3i, lung: H358i and A549i, colon: DLD1i)." (PMID 34326322, 2021). "We observed that inhibition of KIF4A expression reduced clonogenic survival in both AR-dependent and AR-independent prostate cancer models." (PMID 34326322, 2021). "To further investigate why KIF4A is required for prostate cancer proliferation or survival, we measured the transcriptional consequences of KIF4A repression in LNCaPi cells." (PMID 34326322, 2021). "In many malignancies, such as endometrial carcinoma prostate cancer, and glioma, KIF4A is frequently overexpressed and contributes to tumour progression through mechanisms that enhance genomic stability, mediate therapy resistance, and modify the immune microenvironment." (PMID 41361459, 2025). "However, it will be important to model KIF4A in genetically engineered mouse models of prostate cancer to further explore the biology of how KIF4A promotes tumorigenesis, metastasis, and drug response." (PMID 34326322, 2021). "Mechanistically, KIF4A biology is complex and the role of KIF4A in prostate cancer is fairly unknown." (PMID 34326322, 2021). "Collectively, these data suggest that KIF4A may have different functions in primary prostate cancer and mCRPC." (PMID 34326322, 2021). "However, open questions remain with respect to how KIF4A interacts with other proteins to modulate gene expression, chromatin biology, and prostate cancer phenotypes." (PMID 34326322, 2021). "Our data demonstrated that the patterns of open and closed chromatin are broadly remodeled upon KIF4A knockdown suggesting KIF4A may play a role in the regulation of chromatin biology in prostate cancer cells." (PMID 34326322, 2021). "This analysis strategy revealed the Androgen Receptor (AR) as the top prostate cancer-specific gene hit, but the next four top-ranked hits were genes not previously associated with prostate cancer: KIF4A, MRPL13, NDUFB11, and TSR2 (top 5)." (PMID 34326322, 2021). "To test whether repression of KIF4A alters the chromatin landscape of prostate cancer cells, we performed an Assay for Transposase-Accessible Chromatin using sequencing (ATAC-Seq) experiment in LNCaPi and C42Bi cells." (PMID 34326322, 2021).
prostate carcinoma (continued). "In order to demonstrate that the hits identified by these two integrated functional and clinical genomics approaches are potential prostate cancer-specific driver genes, we chose to study KIF4A and WDR62 as they were relatively uncharacterized in the context of mCRPC." (PMID 34326322, 2021). "To experimentally dissect the role of KIF4A in prostate cancer, we tested whether KIF4A expression was required for prostate cancer cell proliferation and or survival in both AR-dependent (LNCaPi, C42Bi, and 22Rv1i) and AR-independent (PC3i and DU145i) cell-line models." (PMID 34326322, 2021). "The occurrence of recurrent long amplicons encompassing more than just AR supports the hypothesis that KIF4A, AR, and possibly additional genes may be a ‘cluster’ of cancer driver genes that are co-amplified on the X-chromosome to drive prostate cancer tumorigenesis." (PMID 34326322, 2021). "Two highlighted hits, KIF4A and WDR62, reported to influence prostate carcinoma survival and aggressive behavior, were also identified in our LNCaP_FGC screen." (PMID 40956611, 2025). "The upregulated gene set included oncogenes such as PIK3CB, FGFRL1, and NCOA2; prostate cancer-related genes such as SPON2, PCAT4, and SCHLAP1; and cell cycle genes such as MKI67, MCM4, KIF4A, CENPF, and FLNB." (PMID 38067373, 2023). "These experiments, combined with clinical data on these genes, serve to nominate KIF4A and WDR62 as prostate cancer-specific driver genes." (PMID 34326322, 2021). "We demonstrated that two of these genes, KIF4A (Kinesin Family Member 4A) and WDR62 (WD Repeat Domain 62), promote aggressive prostate cancer phenotypes in vitro and in vivo." (PMID 34326322, 2021). "Here, the authors perform genome-wide CRISPRi screens and integrate these data with metastatic prostate cancer functional and clinical genomics data to show that KIF4A and WDR62 drive aggressive prostate cancer phenotypes." (PMID 34326322, 2021). "Recent studies reported that an increased expression of KIF4A and KIF15 are potential prognostic factors in prostate cancer and lung adenocarcinoma, respectively." (PMID 32703154, 2020). "In support of this, our data in vitro and in vivo data demonstrated that KIF4A promotes phenotypes associated with poor prognosis in mCRPC, irrespective of AR status, suggesting KIF4A is a driver gene that promotes disease progression in human prostate cancers." (PMID 34326322, 2021). "KIF4A and WDR62 drive aggressive prostate cancer phenotypes irrespective of AR-status." (PMID 34884583, 2021).
glioma (15 papers, 2017 to 2025). A benign or malignant brain and spinal cord tumor that arises from glial cells (astrocytes, oligodendrocytes, ependymal cells). "In summary, these results indicate that high KIF4A expression is significantly associated with poor prognosis in glioma patients and can also be used as a predictor of glioma prognosis." (PMID 38937742, 2024). "Considering that KIF4A overexpression is associated with poor prognosis in glioma patients, the correlations between KIF4A expression and glioma clinical characteristics were further elucidated." (PMID 38937742, 2024). "In the present study, we demonstrated that KIF4A was abnormally overexpressed in glioma and that the overexpression of KIF4A was closely associated with poor prognosis in glioma patients." (PMID 38937742, 2024). "In conclusion, our findings indicated that KIF4A overexpression in glioma is associated with poor prognosis and that targeting KIF4A can inhibit glioma progression." (PMID 38937742, 2024). "Subsequently, univariate and multivariate Cox regression analysis and ROC curve analysis demonstrated that the expression level of KIF4A in glioma can serve as an independent prognostic risk factor for glioma." (PMID 38937742, 2024). "Subsequently, KIF4A expression data, as well as relevant clinical information, including the glioma grade, IDH mutation status, 1p19q codeletion status and patient age, was extracted from the CGGA database." (PMID 38937742, 2024). "Taken together, these results suggested that KIF4A overexpression was closely related to multiple malignancy-associated clinical characteristics of glioma." (PMID 38937742, 2024). "We analyzed the association of KIF4A expression with survival in patients with glioma using online database." (PMID 36606197, 2022). "We also analyzed the association of KIF4A with survival in another glioma cohort, data showed that high KIF4A expression was significantly correlated with poor overall survival (OS) (p = 0.03) and disease-free survival (DFS) (p = 0.02)." (PMID 36606197, 2022). "Taken together, these results suggest that KIF4A is overexpressed in glioma and may be associated with glioma progression." (PMID 38937742, 2024). "Additionally, KIF4A overexpression was significantly associated with a high histological grade and poor prognosis in glioma patients." (PMID 38937742, 2024). "In addition, further analysis confirmed that the expression level of KIF4A is closely related various clinical characteristics of glioma patients, including the IDH mutation status, 1p19q deletion status, and histological grade." (PMID 38937742, 2024). "Furthermore, ROC curves were generated to assess the clinical diagnostic value of KIF4A for glioma in the TCGA and CGGA databases." (PMID 38937742, 2024). "Nonetheless, localized delivery is feasible only for accessible or early-stage tumors and is impractical for metastatic or deeply seated cancers—particularly those such as gliomas or disseminated gastrointestinal tumors, where KIF4A is highly oncogenic." (PMID 41361459, 2025). "In glioma, KIF4A is a crucial oncogene, markedly overexpressed and significantly linked to poor patient prognosis and reduced survival." (PMID 41361459, 2025). "In glioma, KIF4A enhances the expression of BUB1, activating the TGF-β/SMAD pathway, which promotes EMT and malignant progression." (PMID 41361459, 2025). "In glioma models, both WZ-3146 treatment and KIF4A knockdown significantly inhibited tumour cell proliferation and migration while inducing apoptosis via Caspase-3 activation." (PMID 41361459, 2025). "Inhibition of KIF4A can inhibit the progression of glioma, and addition of a small molecule inhibitor of KIF4A induced apoptosis in glioma cells, showing anti-glioma effects." (PMID 40964093, 2025). "The small molecule inhibitor WZ-3146 targets KIF4A, suppressing glioma cell proliferation and inducing apoptosis in vitro via Caspase-3 activation, positioning it as a potential candidate for clinical application." (PMID 41361459, 2025).